CD163 (CD163 molecule)
Diseases named in the same sentence as CD163 in open-access papers (continued):
Sharing a sentence is not in itself a finding about the gene and the disease.
lymph node metastasis (continued). "However, the results in TI did not reveal any significant association between CD163+ TAMs and any clinicopathological characteristics, including histologic grade and lymph node metastasis." (PMID 38501293, 2024). "Elevated CD163+ TAM counts are correlated with advanced FIGO stages and lymph node metastasis, positioning them as potential biomarkers for cervical cancer progression and dissemination." (PMID 40808954, 2025). "In CRC tissues, CD163 was related to tumor TNM stage (χ2 = 23.974, p <0.01), vascular cancer emboli (χ2 = 6.201, p =0.010), neural invasion (χ2 = 4.328, p =0.029), lymph node metastasis (χ2 = 15.663, p =0.002), and distant metastasis (χ2 = 4.273, p =0.029)." (PMID 39104717, 2024). "The adverse prognostic impact of stromal CD163+ TAMs remained significant (RFS: P = 0.02, Wald test) in a multivariate model when correcting for lymph node metastasis, a known clinical prognostic factor in VSCC." (PMID 38407373, 2024). "The number of infiltrating macrophages expressing CD163 or CD204 had a stronger correlation with advanced T category and lymph node metastasis and promote a Th2, pro-tumorigenic or immunosuppressive response." (PMID 37366900, 2023). "The histopathological classification, Lauren classification, lymph node metastasis, CD8 T lymphocyte and CD163 macrophage infiltrations, and MMP-11 expression were significantly associated with the textural features of AGC." (PMID 36010928, 2022). "The counts of total CD163+ macrophages were significantly increased in cases presenting with higher FIGO stages (≥IIA group) and lymph node metastasis (both P=0.04)." (PMID 33928349, 2021). "Cox regression analysis showed that tumor size, differentiation degree, lymph node metastasis, depth of infiltration, TNM stage, CD16- and CD163-positive macrophage density were the independent prognostic factors (P < .05)." (PMID 32332633, 2020). "And the intratumoral density of CD68- and CD163- positive cells in cervical carcinoma with lymph node metastasis was significantly higher than that in non-lymph node metastasis group (both P<0.05)." (PMID 33928349, 2021). "Thus, high stromal and alveolar density of CD163+ TAMs significantly correlated with the C-reactive protein (CRP) level in circulation, the Ki-67 proliferation index and invasive size, tumor differentiation, lymph node metastasis and pathological stage." (PMID 33194645, 2020). "Moreover, CD163-positive TAMs also revealed a significant relationship with T category (RR: 1.41, 95% CI: 1.20 -1.65) but were not related to axillary lymph node metastasis (RR: 1.15, 95% CI: 0.96-1.37) and HER2 expression (RR: 1.26, 95% CI: 0.90-1.78)." (PMID 31528210, 2019).
Cirrhosis (37 papers, 2012 to 2025). A chronic disorder of the liver in which liver tissue becomes scarred and is partially replaced by regenerative nodules and fibrotic tissue resulting in loss of liver function. "Strong inflammatory conditions displayed by high levels of C-reactive protein (CRP) or soluble CD163 (sCD163) are associated with an unfavorable prognosis in patients with cirrhosis." (PMID 26121590, 2015). "IL-6, CD163, and vWF were higher (p <0.01) at baseline in patients with cirrhosis and CSPH compared to those with subclinical PH and controls." (PMID 39850960, 2025). "The macrophage-related serum biomarker soluble CD163 (sCD163) has been shown to differentiate mild liver fibrosis from the cirrhosis in patients with chronic hepatitis C." (PMID 38668286, 2024). "The macrophage activation markers soluble CD163 (sCD163) and mannose receptor (sMR) correlate with the lactulose mannitol ratio, which is a widely used method of assessing IP in patients with cirrhosis." (PMID 36077228, 2022). "CD163 is predominantly expressed on Kupffer cells, which are the resident macrophages in the liver and play a central role in the development of cirrhosis by modulating pro- and anti-inflammatory signals." (PMID 34336902, 2021). "Using multiple logistic regression analysis with backward elimination the combination of sCD163, ALT and INR into a CD163-ALT-INR cirrhosis score resulted in a higher AUROC of 0.80." (PMID 32615997, 2020). "Under the coinfection with human immunodeficiency virus (HIV) or hepatitis C virus (HCV), serum (s)CD163 levels accompanied periportal CD163+ macrophage enrichment was associated with mild to moderate fibrosis, but not cirrhosis." (PMID 33763066, 2021). "Therefore, a high number of CD163+ cells can correlate with fibrosis and cirrhosis, as seen in D09, but their number can also be increased, as seen in D15, without any signs of pathology." (PMID 33918803, 2021). "Successful DAA therapy rapidly normalised the plasma inflammatory milieu, with the notable exception of soluble (s)CD163, a marker of macrophage activation, which remained elevated after viral clearance and segregated patients with high and low levels of cirrhosis." (PMID 32034167, 2020). "The soluble form of two scavenger receptors CD163 and CD206 (sCD163 and sMR/sCD206), expressed by circulating blood monocytes and macrophages, were present in plasma, ascites and other body fluids and associated with severity and prognosis of chronic liver diseases and cirrhosis." (PMID 36926073, 2022). "Another group defined PM subsets as large PMs (LPMs, CD206+CD163+) and small PMs (SPMs, CD206-), which differed in granularity and maturation markers in ascites samples from patients with cirrhosis." (PMID 36926073, 2022). "Frequencies of CD68+, CD163+ M2-polarized TAMs and TILs were measured in de novo HCC tumours in non-cirrhosis (n = 58) using immunohistology and correlated to patients’ clinicopathological characteristics and survival rates." (PMID 31170995, 2019). "However, differences in expression- and shedding-stimuli for CD163 and CD206 may explain dissimilarities in prognostic utility in patients with acute decompensation of cirrhosis and ACLF." (PMID 32397365, 2020). "PoPH macrophage clusters also demonstrated a unique signature, with increased CXCL2 and CD163 expression, and diminished MIF expression, relative to non-PoPH cirrhosis macrophage clusters." (PMID 37558836, 2023). "However, sCD163 and sMR plasma/serum levels have been associated with a variety of other diseases and infection conditions as shedding of CD163 and CD206 is associated with macrophage activation in general and does not specifically indicate immuneparesis in patients with cirrhosis." (PMID 36926073, 2022). "Soluble CD163 and sMR levels are elevated in patients with IPH and patients with cirrhosis, but normal in patients with non-cirrhotic PVT." (PMID 34177608, 2021).
Cirrhosis (continued). "In non-parametric ROC analysis, sCD163 and the CD163-ALT-INR cirrhosis score predicted cirrhosis with an area under the ROC curve of 0.69 (95% confidence interval (CI): 0.59–0.79) and 0.80 (95% CI: 0.71–0.88), respectively (p = 0.02)." (PMID 32615997, 2020).
pancreatic cancer (35 papers, 2017 to 2025). "Our analysis showing that high expression of CD163, which is expressed by M2-type macrophages, in resected pancreatic tumors associated with poor survival is coherent with these previous reports." (PMID 38598844, 2024). "Increased infiltration of CD163+ TAMs in patients with pancreatic cancer is associated with a lower rate for 5-year survival and 5-year recurrence free survival, but the general presence of macrophages, designated by the pan-macrophage marker CD68, does not correlate with survival." (PMID 35008355, 2021). "Furthermore, CD68+ macrophages and especially CD163+ subpopulations were found to be tightly associated with pancreatic cancer cells." (PMID 30899426, 2019). "In support of this hypothesis, we previously reported mRNA IL-1β expression in both the pancreatic tumor epithelial and stromal compartments, and IL-1β staining within the stroma mainly in association with CD163 positive TAMs." (PMID 30760333, 2019). "Therefore, CD163 macrophage-specific high expression might be implicated in initiation of pancreatic cancer." (PMID 39462379, 2024). "Previous study compared CD163 expression in pancreatic cancerous cells and para-cancerous cells and showed significant higher expressions in pancreatic cancer." (PMID 39462379, 2024). "One study observed that CD14+ human peripheral blood mononuclear cells (PBMCs), when co-cultured with fibroblasts from pancreatic cancer tissue, exhibited an increased expression of M2 macrophage phenotype markers CD163 and CD206." (PMID 37108548, 2023). "EpCAM+ cancer cells (PD-L1− or TIM-3−), CD8+ T cells with either PD-1+ or TIM-3+, and CD14+CD68+CD163+TIM-3+ macrophages increased in the MPE of a patient with progressive pancreatic cancer." (PMID 36293034, 2022). "Consistently, T cells, B cells, and DCs were rarely present in metastatic pancreatic cancer, whereas the immunosuppressive cells, including MDSCs (CD11b) and M2-like macrophages (CD163), increased from the donor pancreas to metastatic PDAC." (PMID 35316682, 2022). "Previous studies reported that a high NLR was significantly consistent with accumulation of tumor infiltrating CD66b neutrophils or CD163+ macrophages in patients with PanNEN and pancreatic cancer, which results in poor RFS and OS." (PMID 33789657, 2021). "CD163 hi patients with pancreatic cancer had a shorter DFS (4.5 months vs 12.0 months, P = 0.0043) and OS (11.0 months vs 24.0 months, P = 0.0018) than 163 low patients." (PMID 34778091, 2021). "In the present study, we also confirmed the protein expression of CD163 in patients with pancreatic cancer using IHC, which exhibited increased expression in tumor tissues." (PMID 34778091, 2021). "Next, we investigated the expression of MARCO in relation to the macrophage marker CD163 in a treatment-naïve pancreatic cancer cohort after surgery (n = 65)." (PMID 34778091, 2021). "Activated THP-1 macrophages and pancreatic cancer cells were cocultured in the 0.4-μm transwell system, and the Mφ macrophages cocultured with pancreatic cancer cells became a CD163+ M2 phenotype, which was similar to the phenotype of TAMs in the tumor tissue." (PMID 31685825, 2019). "We also observed that CD59 expression was positively correlated with CD163+ M2 type macrophage infiltration in pancreatic cancer tissues." (PMID 31685825, 2019). "In our present study, Kaplan-Meier survival analysis showed that pancreatic cancer patients with elevated levels of TAMs (indicated by the expression of CD163, CD204, and CD206) or eEF2K, as well as those expressing both CD68 and eEF2K, have poorer overall survival." (PMID 40624025, 2025). "Furthermore, we histologically observed M2‐type macrophage marker CD163 in surgical specimens of pancreatic cancer patients." (PMID 38389400, 2024). "CD163 positive TAM might be a promising prognostic indicator in pancreatic cancer especially when targeted immunotherapy is developed as it will tailor patient specific therapy." (PMID 39462379, 2024).
pancreatic cancer (continued). "Moreover, we showed that sympathetic axons slow pancreatic tumor progression through local suppression of CD163+ macrophage subsets at lesion sites." (PMID 35418199, 2022). "In addition, the expression of the TAM-related biomarkers MRC1/CD206 and CD163 was higher than that in normal human pancreatic tissue, indicating that TAMs are highly infiltrative in pancreatic cancer." (PMID 36324684, 2022). "In addition, we detected the expression of LDHA and CD163 in pancreatic cancer tissues and paired para-tumor normal tissues by IHC staining." (PMID 34592906, 2021). "Immunohistochemical staining of 36 randomly selected pancreatic cancer clinical samples revealed a positive correlation between MMP28 and CD163 (P < 0.05), but a negative correlation between MMP28 and CD86 (P < 0.001), suggesting a close association between MMP28 and CD163 + TAM infiltration." (PMID 39972459, 2025). "A strong correlation was observed between MICAL2 and M2 macrophages biomarker CD163 in the TCGA dataset (r = 0.512, p < 0.05), while immunohistochemistry staining showed that more CD163-positive cells were observed in the MICAL2high patient with pancreatic cancer compared with the MICAL2low patient." (PMID 38326344, 2024). "Taken together, CD163 could predict poor prognosis of pancreatic cancer." (PMID 39462379, 2024). "However, several other known acute-phase reactants were found not to be elevated (e.g., AHSG, SERPINA3, ITIH4, FN, F2, F8, SAP, and CD163), arguing that there may be some specificity in the inflammatory response to pancreatic cancer." (PMID 29232830, 2017). "Increased MMP28 expression, elevated CD163 + TAMs, and reduced CD86 + TAMs were significantly correlated with the pancreatic cancer site (P < 0.05)." (PMID 39972459, 2025). "Pancreatic cancer: In pancreatic ductal adenocarcinoma (PDAC), high CD163 expression, as a marker for M2 macrophages, was inversely correlated with overall survival." (PMID 39451197, 2024). "A large number of CD206 and CD163 positive macrophages, more than CD80 and CD86, were observed in the WT pancreatic tumor and in the corresponding liver metastasis sections, suggesting the relevant presence of M2 macrophages." (PMID 34681678, 2021). "The univariate and multivariate analyses confirmed that combined CD163 and MARCO expression is an independent prognostic marker in pancreatic cancer." (PMID 34778091, 2021). "We observed increased expression of CD163 and MARCO in pancreatic cancer tissues compared with paracancerous tissues." (PMID 34778091, 2021). "Consistent with the increased enrichment of M2 macrophages, the M2 markers of CD163 and CD206 were significantly increased in pancreatic cancer compared with controls." (PMID 34778091, 2021). "Univariate and multivariate analysis revealed that CD163 and MARCO expression was an independent indicator of pancreatic cancer prognosis." (PMID 34778091, 2021). "Nevertheless, the expression of CD163 and MARCO is still a good predictor of pancreatic cancer prognosis." (PMID 34778091, 2021). "We also detected representative markers of THP-1 macrophages (CD163/Arg-1/IFN-γ/iNOS) induced by the pancreatic cancer cells at the mRNA and protein levels, according to the characteristics of TAMs." (PMID 31685825, 2019). "Additionally, comprehensive analysis of pathological staining revealed that anti-CD47 nanobody therapy more effectively reduced the infiltration of F4/80+CD163+ TAMs and increased the infiltration of F4/80+CD86+ TAMs in pancreatic cancer with CCT6A knockdown." (PMID 40374617, 2025). "Furthermore, we observed a large variation in CD163 and MARCO expression in pancreatic cancer tissues among cases, suggesting the heterogeneous expression of these two markers among patients." (PMID 34778091, 2021). "VCAM-1 expression in pancreatic cancer cells also promotes Warburg metabolism, and the lactate released in turn stimulates macrophages to a more immunosuppressive TAM phenotype higher in Cd206, Cd163, and IL-10." (PMID 35008355, 2021).
pancreatic cancer (continued). "Moreover, high CD163 and MARCO expression negatively affected the disease-free survival and overall survival rates of patients with pancreatic cancer." (PMID 34778091, 2021). "Finally, we analyzed the expression profiles of CD163 and MARCO in both cancer and paracancerous tissues from patients with pancreatic cancer." (PMID 34778091, 2021). "Furthermore, we analyzed the combined role of CD163 and MARCO in pancreatic cancer." (PMID 34778091, 2021). "Surprisingly, we found cells that displayed both CD163 and EpCAM immunofluorescence in blood from patients with a variety of types of patients, including breast, cervical, ovarian, endometrial and pancreatic cancer, but not in healthy subjects." (PMID 29137267, 2017). "MARCO and CD163 mRNA expression in PDAC tissues is a negative prognostic marker for pancreatic cancer after surgery, and the application of anti-bodies against MARCO may present itself as an attractive therapeutic approach to remodel the TME towards susceptibility to immunotherapies." (PMID 39457004, 2024). "Subsequent qRT-PCR analysis of 68 pancreatic cancer and adjacent noncancerous tissues samples confirmed elevated MMP28 and CD163 mRNA levels, whereas CD86 mRNA expression was lower in cancer tissues than in noncancerous controls." (PMID 39972459, 2025). "In conclusion, high CD163 and MARCO expression in cancer tissues is a negative prognostic marker for pancreatic cancer after surgery." (PMID 34778091, 2021).